ERG (ETS transcription factor ERG)
Diseases named in the same sentence as ERG in open-access papers (continued):
Sharing a sentence is not in itself a finding about the gene and the disease.
Kaposi's sarcoma (6 papers, 2023 to 2025). A malignant neoplasm characterized by a vascular proliferation which usually contains blunt endothelial cells. "Subsequent PET/CT detected metabolically active nodes on the contralateral side, and additional biopsies confirmed Kaposi sarcoma, with immunohistochemistry positive for CD34 and ERG." (PMID 41246668, 2025). "Immunohistochemically, AH exhibits CD31, CD34, and ERG positivity, but it is negative for HHV-8, CD8, and D2-40, which helps exclude Kaposi sarcoma and lymphatic-derived lesions." (PMID 40364141, 2025).
myeloid leukemia (6 papers, 2011 to 2025). A clonal proliferation of myeloid cells and their precursors in the bone marrow, peripheral blood, and spleen. "Increased expression of ERG causes myeloid leukemias in mice and is associated with poor outcome in human AML; genome‐wide loss of uSTAT5 binding may therefore contribute to the leukemogenic consequences of JAK/STAT activation by increasing access of ETS factors to their target genes." (PMID 26702099, 2016). "Transcriptome analysis of both patient samples and K562 myeloid leukemia cells overexpressing RUNX1::ERG revealed consistent MYC repression by the fusion protein." (PMID 37002311, 2023). "ERG is involved in chromosomal rearrangements in myeloid leukemia, in 5 to 10% of cases of Ewing's sarcoma, resulting in fusion of Erg and a member of the Tet subfamily of RNA-binding proteins." (PMID 22461792, 2012).
bone tumor (5 papers, 2010 to 2025). "Despite these findings, ERG did confer greater enzalutamide sensitivity in VCaP cells and in a VCaP-based in vivo model of bone tumor growth compared to ERG knock-down groups." (PMID 36212399, 2022). "In this study, we tested the biological significance of ERG induced androgen production on bone tumor growth and targeting AR signaling with enzalutamide." (PMID 31638934, 2019). "Western blotting analyzed VCaP bone tumor samples for ERG, AR, AKR1C3 and HSD3B1 and HSD3B2 expression." (PMID 31638934, 2019). "Bone tumor analysis of these enzymes show that ERG knockdown tumors have lower expression, suggesting in vivo function of ERG in maintaining the enzyme expression in bone tumors." (PMID 31638934, 2019). "Furthermore, enzalutamide therapy is more effective in ERG positive bone tumor at inhibiting tumor growth compared to ERG knockdown tumors." (PMID 31638934, 2019). "To determine how ERG induced androgen synthesis contributes to bone tumor growth and whether ERG activity can be a predictor for anti-androgen therapy responsiveness, we utilized an intratibial bone tumor growth model with VCaP scr and ERG shRNA cells to address these questions." (PMID 31638934, 2019). "We utilized ERG knockdown approach in TMPRSS2-ERG positive cells and targeting the AR function with enzalutamide for bone tumor growth." (PMID 31638934, 2019). "Bone tumor analysis shows that ERG knockdown results in diminished expression of AKR1C3 and HSD3B1 in bone tumors." (PMID 31638934, 2019).
erythroleukemia (5 papers, 2018 to 2024). Acute erythroid leukemia characterised by the presence of at least 50% erythroid precursors and at least 20% myeloblasts in the bone marrow. "We further evaluated the functional effects of P199L-ERG on the megakaryocytic lineage by transducing both WT and mutant ERG into K562 cells (erythroleukemia with low expression of endogenous ERG)." (PMID 37735473, 2023). "Interestingly, the Jak2 gene locus was among the most common CIS in this model furthermore underlining cooperation of ERG and constitutively active JAK2 in murine erythroleukemia." (PMID 33898929, 2021). "These in silico findings suggest the possibility that LSD1 could suppress the ERG-SE by forming the complex with GFI1B in erythroleukemia cells." (PMID 29765516, 2018).
glioblastoma (5 papers, 2011 to 2024). The most malignant astrocytic tumor (WHO grade IV). "ERG is upregulated in central nervous system tumors, including glioblastomas and hemangioblastomas, and may function as a specific marker in these tumors." (PMID 30237984, 2018).
hemangioma (5 papers, 2024 to 2025). A benign vascular lesion characterized by the formation of capillary-sized or cavernous vascular channels. "Immunohistochemical staining for CD31 and ERG and molecular pathology revealed a somatic mutation at codon 209 of the GNAQ gene usually supports the diagnosis of hemangioma." (PMID 40797498, 2025). "Additionally, the tumor displayed positive immunoreactivity for ERG, a transcription factor with high sensitivity and specificity for vascular lesions, with studies showing 100% expression of ERG in endothelia of hemangiomas." (PMID 40046370, 2025). "Positive immunohistochemical staining for CD34, CD31, and ERG may support the diagnosis of hemangioma." (PMID 38533349, 2024).
schizophrenia (5 papers, 2012 to 2022). A major psychotic disorder characterized by abnormalities in the perception or expression of reality. "While the location of most frequent schizophrenia-associated ERG mutation is located on a non-coding (intron) site, previous work demonstrated that this mutation promoted transcription from an alternative transcription start site." (PMID 31032798, 2019). "More importantly, an association between ERG mutations and schizophrenia has been established." (PMID 36499661, 2022). "Furthermore, the eag domain-CNBHD interface of ERG channels is altered in some forms of long QT syndrome and schizophrenia." (PMID 28443815, 2017). "In previous SNP level analyses, ERG, NEBL, CADPS2, GABBR2, and HDAC9 genes have been reported to be related with neuropsychiatric diseases such as BD, depression disorder, and schizophrenia." (PMID 22901090, 2012).
small cell carcinoma (5 papers, 2011 to 2022). A neuroendocrine carcinoma composed of small malignant cells which are often said to resemble "oat cells" under the microscope. "In patients with mixed adenocarcinoma and small cell carcinoma, the ERG status was highly congruent." (PMID 35109899, 2022).
COVID-19 (4 papers, 2021 to 2025). A disease caused by infection with severe acute respiratory syndrome coronavirus 2. "We found that higher expression levels in ERG increased the risk of severe COVID-19 which is described for the first time with this role." (PMID 37287057, 2023). "Here we focus on TMPRSS2, and related genes ACE2, MX1, AR, ETV5 and ERG, by its own or combined with clinical data, as an easy and relevant classifier of COVID-19 aggressiveness." (PMID 37287057, 2023). "Here we characterize the role of ACE2, AR, MX1, ERG, ETV5 and TMPRSS2 for trying a better classification of COVID-19 through knowledge of the disease mechanisms." (PMID 37287057, 2023).
hepatocellular carcinoma (4 papers, 2016 to 2025). A malignant tumor that arises from hepatocytes. "miR-200b is known decreased in hepatocellular carcinoma (HCC), however, the functional relation between ERG and miR-200b-3p, originating from pre-miR-200b, in HCC angiogenesis remains unclear." (PMID 32591615, 2020).
mesenchymal tumors (4 papers, 2019 to 2025). "Herein, we present a case of an acral chondromyxoid mesenchymal neoplasm harboring a novel in-frame TCF4::ERG fusion involving the right index finger of a 26-year-old female." (PMID 40878874, 2025). "Only CD31, ERG, Ki-67, and Desmin were positive, and malignant mesenchymal tumor was considered." (PMID 38788046, 2024). "The proportion of repeat regions within the breakpoint cluster regions was 25% for TMPRSS2 and 34% for ERG, which is comparable to other mesenchymal tumors for which DNA-level genomic fusion sequences have been successfully established as patient-specific biomarkers (Supplemental )." (PMID 31915468, 2019).
multiple myeloma (4 papers, 2018 to 2025). "We assessed the function of ERG in U266 and RPMI8226 myeloma cell lines using siRNA interference and discovered that the inhibition of ERG significantly reduced the invasion and migration capabilities of the cells." (PMID 40741330, 2025). "Lastly, validation in larger, well-annotated clinical cohorts is essential to confirm ERG’s prognostic and therapeutic relevance in multiple myeloma." (PMID 40741330, 2025). "The experimental results indicated that reducing ERG protein expression diminished the invasion and migration capabilities of the myeloma cell lines." (PMID 40741330, 2025). "The TF with the largest weight in the model is the ETS-related gene (ERG), which is shown to be essential for early B lymphoid differentiation and nuclear expression of ERG in a vast majority of myeloma cells." (PMID 35627314, 2022). "By utilizing siRNA to disrupt ERG expression in U266 and RPMI8226 cell lines, we evaluated the effects of the master regulator ERG on the proliferation, apoptosis, invasion, and migration of myeloma cell lines, and we confirmed the expression of ERG in patients with extramedullary MM." (PMID 40741330, 2025).
myelodysplastic syndrome (4 papers, 2018 to 2023). A clonal hematopoietic disorder characterized by dysplasia and ineffective hematopoiesis in one or more of the hematopoietic cell lines. "ERG encodes a proto-oncogenic transcription factor expressed in hematopoietic stem cells including those present in AML and myelodysplastic syndrome (MDS) ERG overexpression has been shown to be an adverse biomarker for cytogenetically normal AML." (PMID 35799207, 2022).
acinar adenocarcinoma (3 papers, 2018 to 2025). "PTEN loss and ERG expression have been described less frequently in ductal carcinoma compared to acinar carcinoma; however, both markers may be observed in ductal carcinoma; hence, they cannot be used as a reliable factor for differential diagnosis between the two entities." (PMID 35804812, 2022). "Radical prostatectomy on November 1, 2024 revealed a small residual acinar adenocarcinoma focus with perineural invasion, negative surgical margins, and molecular evidence of TMPRSS2::ERG gene fusion and PTEN loss." (PMID 41267989, 2025). "At the molecular level, basal cell carcinoma shows a basal cell gene signature with genetic aberrations that are distinct from acinar adenocarcinoma, i.e., frequent EGFR overexpression and absence of ERG rearrangements." (PMID 35804812, 2022).
acute megakaryoblastic leukemia (3 papers, 2016 to 2022). Acute megakaryoblastic leukemia (AMKL) is a form of acute myeloid leukemia (AML) that occurs predominantly in childhood and particularly in children with Down syndrome (DS-AMKL). "ERG is also strongly implicated in the development of the acute megakaryocytic leukemia in children with constitutional trisomy of chromosome 21 where ERG gene resides." (PMID 27494621, 2016).
acute T cell lymphoblastic leukemia (3 papers, 2015 to 2020). "The transcription factor ERG is important for hematopoiesis, and the expression of this oncogene is associated with both AML and acute T cell lymphoblastic leukemia." (PMID 27386562, 2016).
atherosclerosis (3 papers, 2018 to 2022). A disease characterized by the build-up of fatty material and calcium deposition in the arterial wall resulting in partial or complete occlusion of the arterial lumen. "Loss of ERG expression is associated with diseases including atherosclerosis." (PMID 30892142, 2019). "Our analysis of ERG-bound super-enhancers revealed enrichment for SNPs associated with diseases that have a vascular component, including predisposition to CVDs, such as atherosclerosis and coronary artery disease." (PMID 30892142, 2019). "Moreover, ERG expression is lost in other pathological diseases, such as atherosclerosis, chronic liver disease and pulmonary arterial hypertension." (PMID 35723257, 2022).
colon cancer (3 papers, 2022 to 2025). "The transcription factor known as ERG, which is produced by the ERG gene, was initially identified in colon cancer cells in 1987 and is recognized as a new member of the E-26 transformation-specific (ETS) oncogene family." (PMID 39963114, 2025).
hemangioendothelioma (3 papers, 2015 to 2025). A vascular proliferation characterized by the presence of prominent endothelial cells and the formation of vascular channels. "The lack of CD34 and ERG immunopositivity in conjunction with the histological appearance ruled out hemangioendothelioma." (PMID 26187280, 2015).
lymphedema (3 papers, 2023 to 2025). Excess fluid collection in tissues, causing swelling. "The impact of loss of Erg and Fli1 function on lymphatic development in mice is consistent with FOXC2 mutations in lymphedema-distichiasis syndrome or ERG gene variants underlying primary lymphedema in humans." (PMID 41460562, 2025). "In other diseases, ERG-dependent transcription has been shown to modulate cardiovascular disease, and germline LOF ERG variants have been reported to lead to lymphedema, see also in ~10-15% of germline GATA2 cases." (PMID 37377909, 2023).
Sepsis (3 papers, 2022 to 2024). Sepsis is defined as life-threatening organ dysfunction caused by a dysregulated host response to infection. "Double immunofluorescence staining for c-Jun and ERG showed that in the first 24 h of CLP-induced sepsis, positive nuclei in alveolar capillaries were partly derived from EC and partly from non-endothelial cells." (PMID 39200137, 2024). "The results indicated that the ERG signature was an independent of risk factor for outcome of sepsis." (PMID 38011291, 2023). "The MEgrey60 module was more highly expressed in critical COVID-19 than sepsis, and the ETS transcription factor related gene ERG, which regulates lineage plasticity, showed the highest intramodule connectivity." (PMID 35216673, 2022).
small cell carcinoma of the prostate (3 papers, 2011 to 2025). "Similar to reports on small cell carcinoma of the prostate with ERG rearrangements, ERG staining was positive in adenocarcinoma expressing AR but negative in carcinosarcoma lacking AR expression, supporting phenotypic transdifferentiation of cell lineage from adenocarcinoma." (PMID 40969255, 2025).
acinar prostate adenocarcinomas (2 papers, 2014 to 2019). "In the present study we aimed to evaluate the ERG overexpression in 78 cases prostate acinar adenocarcinoma and its association with other prognostic parameters." (PMID 30658688, 2019). "Therefore in the present study we aimed to evaluate the ERG overexpression in prostate acinar adenocarcinoma and its association with other prognostic parameters." (PMID 30658688, 2019). "We found a significant proportion of our patients of prostatic acinar adenocarcinoma to over-express ERG protein which can help in devising therapeutic protocols." (PMID 30658688, 2019). "In the present study, we evaluated the ERG protein expression in 78 cases of prostatic acinar adenocarcinoma." (PMID 30658688, 2019). "A significant proportion of cases of prostatic acinar adenocarcinoma in our studied population were found to have ERG protein overexpression." (PMID 30658688, 2019). "However, we found a significant proportion of our patients of prostatic acinar adenocarcinoma to overexpress ERG protein which can help in devising therapeutic protocols." (PMID 30658688, 2019).
cholangiocarcinoma (2 papers, 2023). A carcinoma that arises from the intrahepatic biliary tree (intrahepatic cholangiocarcinoma) or from the junction, or adjacent to the junction, of the right and left hepatic ducts (hilar cholangiocarcinoma). "In cholangiocarcinoma, lncRNA SNHG3 can competitively adsorb miR-3173-5p (a tumour suppressor miRNA), release its inhibitory effect on the oncogene ERG, and promote the malignant phenotype of cancer cells." (PMID 36447000, 2023).
Cirrhosis (2 papers, 2022 to 2025). A chronic disorder of the liver in which liver tissue becomes scarred and is partially replaced by regenerative nodules and fibrotic tissue resulting in loss of liver function. "Several oncogenic transcription factors (TFs) inferred with DoRothEA35 including FOS, ETS2, RELB, SOX10, ERG, WT1 and JUND and TFs supporting stemness such as PBPJ and ARID3A were upregulated in cirrhosis patients and correlated with bacterial translocation." (PMID 35803930, 2022).
dementia (2 papers, 2022). Loss of intellectual abilities interfering with an individual's social and occupational functions. "To specifically enrich our samples in endothelial cells and microglia, with their important role in dementia and white matter disease, we immunolabeled the nuclei using an antibody against ERG/FLI1 (EPR3864) and FACS sorted these cells." (PMID 35543222, 2022). "Not only the APP gene is responsible for dementia in DS, GATD3A, SOD1, ERG, BACE2, DSCR1/RCAN1, APOE (19q13.32), BACE1 (11q23.3), IL1B (2q14.1), GSAP (7q11.23), UBB (17p11.2), and IRS1 (2q36.3) genes may also play a major role in dementia in DS." (PMID 35676933, 2022).
desmoplastic small round cell tumor (2 papers, 2018 to 2020). Desmoplastic small round cell tumor (DSRCT) is an aggressive soft tissue cancer that typically arises in serous lined surfaces of the abdominal or pelvic peritoneum, and spreads to the omentum, lymph nodes and hematogenously disseminates especially to the liver. "As EWSR1 rearrangement may be found in other tumors such as desmoplastic small round cell tumors, a detection of fusion types (EWSR1/FLI-1 and EWSR1/ERG) from RNA is necessary to confirm the diagnosis using reverse transcription polymerase chain reaction (RT-PCR), which is a highly specific method." (PMID 30319719, 2018).
endometriosis (2 papers, 2020 to 2023). The growth of functional endometrial tissue in anatomic sites outside the uterine body. "Seven genes, namely, APPL1, CSNK2A1, ERG, KDM4A, SMARCC1, SUZ12 and TRIM25, were selected to establish the diagnostic model for endometriosis, and a nomogram was constructed based on them." (PMID 36860677, 2023). "miR-20a via ERG/HLX/STAT4/perforin axis could mediate the cytotoxicity of natural killer (NK) cells in endometriosis." (PMID 32850438, 2020).
iron deficiency (2 papers, 2020 to 2023). "Genome-wide expression studies have shown that the expression of ERG genes is altered in response to iron deficiency." (PMID 32679672, 2020). "In this sense, a recent global kinetic study of gene expression during the progress of iron deficiency has shown that the pattern of expression differs among ERG genes and depends on the severity of the depletion." (PMID 32679672, 2020). "Under conditions of iron deficiency, Hap1 switches from an activator to a repressor of ERG genes." (PMID 37750721, 2023).
liver cancer (2 papers, 2017 to 2021). An epithelial or non-epithelial malignant neoplasm that arises from the liver. "Other studies have shown that exo-miR-200b-3p from liver cells inhibit the expression of endothelial transcription factor ERG, and the reduction of exo-miR-200b-3p in cancer cells promotes the blood vessels of liver cancer tissues by enhancing the expression of endothelial ERG generate." (PMID 33964930, 2021).
lung adenocarcinoma (2 papers, 2015 to 2021). A carcinoma that arises from the lung and is characterized by the presence of malignant glandular epithelial cells. "Three possible lung adenocarcinoma-related DEGs including ERG, STARD8 and THBS2 were identified." (PMID 26035298, 2015).